DOCK2 (dedicator of cytokinesis 2)
Diseases named in the same sentence as DOCK2 in open-access papers (continued):
Sharing a sentence is not in itself a finding about the gene and the disease.
tumor (continued). "In conclusion, the present study identifies a novel prognostic signature in light of DOCK2 mutation-related genes that shows great prognostic value in HCC patients; and this gene mutation might promote tumor progression by influencing immune responses." (PMID 35620462, 2022). "It was also found that the levels of DOCK2 methylation also increased positively with increasing tumor volume, revealing that hypermethylated DOCK2 may be an independent predictor of MPCA progression." (PMID 36250020, 2022). "In conclusion, the present study identifies a novel prognostic signature based on DOCK2 mutation-related genes that shows great prognostic value in HCC patients, and this gene mutation might promote tumor progression by influencing immune responses." (PMID 35620462, 2022). "Tumor formation of DOCK2-KD Ramos cells was also significantly reduced in a xenograft mouse model." (PMID 36250020, 2022). "Interestingly, the mutation observed in the lowest number of reads from the WGS data (DOCK2, mutant allele 10%) is homozygous wild-type in MFD-1, suggesting that the cell line is likely derived from the dominant clone in the tumour." (PMID 27600491, 2016). "Among them, two significantly mutated genes are ELMO1 and DOCK2, encoding dimerization partners and intracellular mediators of the Rho family; ELMO1 or DOCK2 are mutated in 17% of cases, and their mutation determines an enhancement of cellular motility and favors tumor invasion." (PMID 28930282, 2017). "Colonic organoids were derived from control and Dock2tm1a/tm1a (Dock2) mice and Apc deleted using CRISPR to mimic tumour development in an inflammation naïve setting." (PMID 39242821, 2024). "TCGA data reveal that DOCK2 is significantly down-regulated in CRC and that this downregulation facilitates tumor escape and spread." (PMID 36250020, 2022). "The expression of Trgv1, the gene encoding T cell receptor Vγ1 chain, but not Trgv4, Trgv5, Trgv6 or Trgv7 was also upregulated in tumours of Vil Apc Dock2 mice." (PMID 39242821, 2024). "We first investigated lymphoid and myeloid cell populations using immunohistochemistry and found an increase in intratumoural CD3 + T cell infiltration in Vil Apc Dock2 tumours but not of macrophages or neutrophils." (PMID 39242821, 2024). "It is not clear why more IFNγ producing T cells accumulate in tumours formed in Dock2 mutant mice, a gene that is expressed primarily in hematopoietic cells." (PMID 39242821, 2024). "In addition to analyzing the tumor-suppressive effects of ABR, PREX1, DOCK2, and DOCK4 through bioinformatics, we further verified the role of ABR in proliferation, migration, and cloning ability in PC9 and H1703 cells experimentally." (PMID 34783629, 2021). "Finally, the PPI network suggests pivotal roles for DOCK2 and PTPRC dysregulation in the progression of CRC, possibly by facilitating tumor escape from immune surveillance." (PMID 33968341, 2021). "Other genes in the area include PDGFRB, which plays an important role in tumor neovascularization, TGFBI, PTTG1, DOCK2 and DUSP1 (the latter three genes were speculated based on our internal studies), which were likely to be involved in ccRCC progression and development." (PMID 20671976, 2010). "In mice lacking Dock2, IFNγ production is increased in multiple T cell populations, including CD8+ and γδ T cells, and administrating IFNγ to tumour organoids induces robust IDO1 expression suggesting this response is driven by immune cell IFNγ production." (PMID 39242821, 2024). "In support of this, the difference in tumor growth between E0771-SULT and E0771-MOCK disappeared when transplanted into nude mice lacking T cells or DOCK2–/– mice." (PMID 35094065, 2022).
infection (10 papers, 2016 to 2025). The state of being infected such as from the introduction of a foreign agent such as serum, vaccine, antigenic substance or organism. "The literature search yielded 14 DOCK2-deficient patients suffering from both cellular and humoral immune defects leading to early-onset infections, particularly human herpesvirus (HHV) infection." (PMID 34872585, 2021). "In summary, DOCK2 deficiency should be contemplated in the context of severe or unusual early-onset infections, especially HHV infections, accompanied by laboratory data indicating both cellular and humoral defects." (PMID 34872585, 2021). "Here, we report a 27 months old girl who presented with severe infection and carried a novel homozygous frameshift deletion c.1512delG (p.I505Sfs*28) mutation at exon 16 of the DOCK2 gene." (PMID 34872585, 2021). "These immunological disturbances commence early-onset and severe infections in patients harboring DOCK2 mutations that often lead them to death." (PMID 34872585, 2021). "Compared with WT mice, Dock2−/− mice were significantly more susceptible, with 39% of the Dock2−/− mice succumbing to the infection by day 13 (P < 0.01)." (PMID 27291827, 2016). "The risk variant could potentially induce DOCK2 downregulation in early phase of infection." (PMID 35940203, 2022). "Dock2 mice were previously shown to have reduced neutrophil recruitment in an infection model, but this is the first demonstration of its importance in sterile inflammation." (PMID 37383235, 2023). "A genetic mutation in a potential novel HLH-associated gene, dedicator of cytokinesis 2 (DOCK2), was identified in a patient with recurrent episodes of sHLH and hyperinflammation in the setting of frequent central line infections." (PMID 36836791, 2023). "Dedicator of cytokinesis 2 (DOCK2) deficiency is an inborn error of immunity characterized by cellular and humoral immunological abnormalities leading to early-onset infections." (PMID 34872585, 2021). "We observed that the relative distribution of both immune cell types in the mucosa and submucosa was similar in WT and Dock2−/− mice 7 days post-infection." (PMID 27291827, 2016). "Both macrophages and neutrophils were found in the colon of WT and Dock2−/− mice 7 days after infection." (PMID 27291827, 2016). "We observed an increased frequency of Tir staining covering the intestinal epithelial surface of the distal colon in Dock2−/− mice compared with WT mice 4 days post-infection." (PMID 27291827, 2016). "Remarkably, we frequently identified attachment of C. rodentium to microvilli and induction of pedestal-like structures on enterocytes along the colon of Dock2−/− mice 4 and 7 days after infection." (PMID 27291827, 2016). "DOCK2 mutations have been implicated in prior cases of HLH and severe infection." (PMID 36836791, 2023). "Our observational and interventional findings on DOCK2 downregulation show that in COVID-19 pneumonia pathophysiology, impaired macrophage recruitment at the site of infection and dysregulated IFN responses result in impaired virus elimination and prolonged lung inflammation." (PMID 35940203, 2022). "Compared to WT mice, DOCK2−/−mice had significant bacterial adherence to mucosal microvilli early in the infection, which partially explains the increased susceptibility of DOCK2−/−mice to Citrobacter infection early in the infection." (PMID 36250020, 2022). "Increased virtual memory CD8+T cell expression of DOCK2-deficient mice was associated with increased resistance to Listeria monocytogenes, with the higher secretion of types of interferon (IFN)-γ against intracellular bacterial after infection." (PMID 36250020, 2022). "However, on day 21 after infection, the C. rodentium load of WT mice transferred with Dock2−/− mouse microbiota was significantly higher." (PMID 34391464, 2021). "Dock2−/− mice lost body weight, especially 10 days after infection." (PMID 27291827, 2016).
infection (continued). "However, we found similar levels of these mediators in the colon tissues of WT and Dock2−/− mice 4 days after infection and increased expression of these mediators after 14 days of infection." (PMID 27291827, 2016). "However, we found a reduced proportion of the total macrophages and neutrophils infiltrating the mucosa in infected Dock2−/− mice compared with infected WT mice 14 days after infection." (PMID 27291827, 2016). "Overall, DOCK2 deficiency did not impair the production of protective pro-inflammatory cytokines and anti-microbial peptides at earlier time points during the infection." (PMID 27291827, 2016). "The differential ability of macrophages and neutrophils to infiltrate the mucosa in WT and Dock2−/− mice at the later stages of infection could be influenced, in part, by earlier events that establish the infection." (PMID 27291827, 2016). "The product of the dedicator of cytokinesis 2 gene (DOCK2) is crucial in immune response by mediating the differentiation of T cells and lymphocyte migration to sites of infection." (PMID 30598788, 2018). "We found similar levels of IL-17 and IFN-γ in the colon tissues of infected WT mice and Dock2−/− mice and elevated levels of TNF in the colon tissues of infected Dock2−/− mice compared with WT mice 14 days post-infection." (PMID 27291827, 2016). "We infected WT and Dock2−/− mice via oral gavage with 1 × 1010 CFU C. rodentium per mouse, harvested the spleen, liver and mesenteric lymph nodes (MLNs) 14 days post-infection and analyzed the presence of viable bacteria." (PMID 27291827, 2016). "Additionally, genes such as DOCK2, ARHGAP24, and KCTD18 regulate cytoskeletal reorganization and cell migration, ensuring that immune cells effectively reach infection or inflammation sites." (PMID 40098976, 2025). "However, BMDMs from DOCK2−/− mice had defects secretion of chemokines CCL4 and CCL5 after infection, which was partially restored upon adoptive transfer of wild-type BMDMs." (PMID 36250020, 2022). "Our results showed that both WT and Dock2−/− mice treated with antibiotic could not clear C. rodentium on days 5, 10 and 17 day after infection, which indicated that removal of gut microbiota reversed the difference of bacterial loads." (PMID 34391464, 2021). "However, WT mice cohoused with Dock2−/− mice had significantly more C. rodentium load than those not cohoused at 10, 14, and 17 days after infection." (PMID 34391464, 2021).
bacterial infections (2 papers, 2022 to 2025). "Although DOCK2 protected against LPS-induced shock via blunting the cytokine storm, especially IFN-γ response, the role of DOCK2 in resisting live bacterial infections remains largely unknown." (PMID 40510337, 2025).
infectious disease (2 papers, 2016 to 2023). A disorder directly resulting from the presence and activity of a microbial, viral, or parasitic agent in humans. "Additional clues for a role of DOCK2 in immunity to infectious disease were highlighted in a study showing that a virulence factor known as Nef encoded by HIV-1 associates with DOCK2 to inhibit chemotaxis of T cells." (PMID 27291827, 2016). "However, the role of DOCK2 in infectious disease is largely unexplored." (PMID 27291827, 2016). "However, the physiological function of DOCK2 in infectious diseases has remained undefined." (PMID 27291827, 2016). "However, the function of DOCK2 in immunity to infectious diseases remains unknown." (PMID 27291827, 2016). "Together, the data from mice suggest that lack of Dock2 activity reduces neutrophil recruitment during inflammatory and infectious diseases, as well as the neutrophil effector responses that clear pathogens." (PMID 37383235, 2023).
autosomal recessive disease (1 paper, 2021). Autosomal recessive form of disease. "Another patient had unrevealing genetic workup including whole exome sequencing and a targeted SCID genetic panel, which showed heterozygous variants of unknown significance in DOCK2 and Artemis that are typically associated with autosomal recessive disease." (PMID 34539671, 2021).
intestinal disease (1 paper, 2021). "Our results indicated that Dock2 deficiency should be added to the list of host genetic factors that may drive alterations in the gut microbiota, which in turn may promote intestinal disease." (PMID 34391464, 2021).
DOCK2 also shares sentences with these, for which no sentence is quoted: benign prostatic hyperplasia (2 papers); idiopathic pulmonary fibrosis (2); lymphoma (2); Primary immunodeficiencies (2); acute respiratory distress syndrome (1); asthma (1); atherosclerosis (1); autoimmune disease (1); autoimmune vasculitis (1); chronic kidney disease (1); colonic (1); colorectal tumors (1); diabetes (1); diffuse large B-cell lymphoma (1); edema (1); endotoxemia (1); esophageal adenocarcinoma (1); fibrosis (1); Hemophagocytic Lymphohistiocytosis (1); Hepatitis (1); hepatocellular carcinoma (1); HIV-1 infection (1); inflammatory bowel disease (1); ischemia (1); neurological diseases (1); schizophrenia (1); septic shock (1); skeletal tuberculosis (1); T-cell lymphoma (1); ulcer (1).
A further 1 disease shares a sentence with DOCK2 in 1 paper.